OR13C7 (olfactory receptor family 13 subfamily C member 7 (gene/pseudogene))
Description:
Odorant receptor.
Synonyms: OR13C7P; OST706; OR37C
Gene: Protein-coding gene on chromosome 9 (36,002,909 to 36,003,867, reverse strand). Ensembl gene ENSG00000243641.
Subcellular location: Cell membrane
Homologues: Orthologues: mouse Or13c7c (48% identical), rat Or13c7c (48% identical), dog OR13C7G (47% identical). Paralogues in human: OR2S2 (47% identical), OR13C2 (41% identical), OR13C5 (40% identical), OR13C9 (40% identical), OR13C4 (39% identical), OR13C3 (39% identical), OR13C8 (39% identical), OR2C3 (36% identical), OR2D2 (35% identical), OR2H2 (35% identical), OR2J1 (35% identical), OR2J2 (35% identical), and 80 more.